SMASR (SMAD3 associated long non-coding RNA)
Synonyms: LINC02206
Gene: Long non-coding RNA gene on chromosome 15 (66,931,508 to 66,957,324, reverse strand). Ensembl gene ENSG00000259289.
Diseases named in the same sentence as SMASR in open-access papers:
SMASR is named in the same sentence as 1 disease in open-access papers, as found by Europe PMC text mining. Sharing a sentence is not in itself a finding about the gene and the disease. The quoted sentences say what the papers report.
lung carcinoma (4 papers, 2022 to 2025). "LncRNA SMASR inhibits lung cancer progression by negatively regulating TGF‐β/Smad signaling." (PMID 35293026, 2022). "This evidence suggests that SMASR could be applicable as a novel EMT marker and a promising lung cancer therapeutic." (PMID 39083441, 2025). "Importantly, SMASR inhibits the TGFβRI by interacting with Smad2/3, leading to the inactivation of the TGFβ/SMAD signaling pathway and forming a negative feedback loop, which plays a critical role in regulating EMT in lung cancer." (PMID 39083441, 2025).